ICAM1 (intercellular adhesion molecule 1)
Diseases named in the same sentence as ICAM1 in open-access papers (continued):
Sharing a sentence is not in itself a finding about the gene and the disease.
cancer (continued). "The underlying mechanism involves cannabinoid-induced upregulation of the intercellular adhesion molecule 1 (ICAM-1) on cancer cell surfaces and the following interaction with lymphocyte function-associated antigen 1 (LFA-1) on the outside of killer cells." (PMID 33802014, 2021). "We also revealed the crosstalk between fibroblasts and cancer cells via ICAM1/AREG and collagen/integrin." (PMID 34326696, 2021). "Cancer cells promote neutrophil ET formation and are closely related to the inflammatory cytokines ICAM-1, VCAM-1, E-selectin, IL1, IL6, CXCL1, and C3a receptors." (PMID 34084158, 2021). "In HCC, ICR specifically affects cancer stem cell properties of ICAM-1(+) HCC cells and lncRNA ICR contributes to portal vein tumor thrombus development." (PMID 34532296, 2021). "Among them, five targets (APOH, CD14, ICAM1, LRG1 and SERPINC1) were reported to be associated with other cancers or prognostic significance." (PMID 34199928, 2021). "The expressions of cell adhesion molecules, especially ALCAM (activated leukocyte cell adhesion molecule) and ICAM1 (intercellular adhesion molecule 1), which have been reported to play vital roles in cancer cell adhesion, were remarkably downregulated." (PMID 33809909, 2021). "TANs can initiate cancer metastasis through MAC-1/ICAM-1 axis-mediated cell-to-cell communication between TANs and cancer cells." (PMID 34063848, 2021). "We further screened the activated ligand-receptor pairs between ductal cells and these two stroma-cell types and defined several cancer-associated pairs, such as EGFR/TGFB1, ANXA1/FPR3, EREG/EGFR, and ICAM1/AREG." (PMID 34326696, 2021). "We demonstrated that the actin–transgelin-2–LFA-1 axis in cytotoxic CD8+ T cells is effective in potentiating adoptive T cell therapy in cases where cancer cells express ICAM-1 on their surface." (PMID 33731208, 2021). "Another important molecule in terms of cancer and inflammation is intercellular adhesion molecule 1 (ICAM-1)." (PMID 33670434, 2021). "Another important mechanism that we identified among the LR biomarkers is the stimulation of LFA-1 (encoded by ITGAL and ITGB2 genes) by ICAM (ICAM2 → ITGAL, ICAM1_ICAM3 → ITGAL, and ICAM3 → ITGB2 in 18, 11, and 8 cancer types, respectively)." (PMID 34430923, 2021). "Several cancer-associated mRNAs were found using the RISCTRAP assay, including ICAM1, SUMO3, HIF1A, and SEC23A." (PMID 34831007, 2021). "For example, the CAMs pathway enables cancer cells to attach to the endothelium in the target organ, and the Ig-CAMs (ICAM1, ICAM3) have important roles in this process." (PMID 33413400, 2021). "The interaction between intercellular adhesion molecule-1 (ICAM-1) and mucin 1 facilitates the migration of cancer cells through the vessel walls and favors metastasis and cancer progression." (PMID 34770912, 2021). "Intercellular adhesion molecule-1 is an important transporter that is upregulated in several types of cancers." (PMID 33072116, 2020). "For example, several cancer cells’ surface-expressed integrins (such as αvβ3, β5 integrins), ligand sialyl Lewis (sLex), and endothelial receptors (ICAM-1,VCAM-1) reportedly contribute to the adhesion of cancer cells to endothelia." (PMID 33379338, 2020). "Cancer cell trans-endothelial migration was reduced when using flowed osteocytes conditioned medium, which was abolished when blocking intercellular adhesion molecule 1 (ICAM-1) and interleukin 6 in the medium." (PMID 31936342, 2020). "ICAM1, which is identified in cell lines as well as patients’ urine data, is known to promote tumorigenesis and increase the metastatic potential of cancer cells." (PMID 32922663, 2020). "MSI1 was shown to be a direct translational activator of ICAM1, a cell surface protein directly involved in cancer cell migration." (PMID 33317545, 2020). "Induction of ICAM-1 expression by VEGF-A inhibition is an emerging aspect that supports the association of immunotherapy and anti-angiogenic therapy in cancer treatment." (PMID 32352958, 2020).
cancer (continued). "Among several known adhesion molecules, ICAM-1 is important in interactions between cancer and endothelial cells." (PMID 33023153, 2020). "Irradiation of a number of human cancer cells has been shown to induce ICAM-1 expression, which enhances activated NK cell-mediated cytotoxicity." (PMID 32135474, 2020). "The utility of ICAM1 as a target can be extended to other advanced cancers and to other immunotherapeutics including CAR‐T cells or bi‐specific antibodies directed toward ICAM1." (PMID 33344137, 2020). "High levels of ICAM-1 were correlated with advanced stage and poor prognosis in multiple types of cancer." (PMID 33680949, 2020). "CAVATEK binds to cancer cells by interacting with intercellular adhesion molecule 1 (ICAM-1) and decay-accelerating factor (DAF)." (PMID 33207653, 2020). "ICAM-1, as an adhesion molecule of the immunoglobulin superfamily, is critically involved in both cancer metastasis and atherogenesis." (PMID 32855961, 2020). "Many malignant tumors are related to increased expression of intercellular adhesion molecule-1 (ICAM1), providing a rationale for ICAM1-specific immunotherapies for the treatment of cancer." (PMID 33072116, 2020). "Recent studies revealed that ICAM-1 expression plays an important role in interactions between lymphokine-activated killer cells and cancer cells." (PMID 31297450, 2019). "Our findings indicate that repression of ICAM1 is a critical mechanism by which cancer cells evade attack from NK cells during tumorigenesis." (PMID 31619256, 2019). "A soluble form of ICAM-1 (sICAM-1) is present in elevated concentrations in the sera of different kinds of cancers, for example, gastric cancer, pancreatic cancer, melanoma, and CRC." (PMID 30470940, 2019). "Herein, we showed that repression of ICAM1 is a critical mechanism by which cancer cells evade attack from NK cells during tumorigenesis." (PMID 31619256, 2019). "There is another research subsequently conducted which confirms the interaction between MAC-1 and ICAM1 (neutrophils and cancer cells, respectively)." (PMID 31474975, 2019). "Proteomic analysis of the content of these exosomes identified several established cancer- related proteins (i.e., IL-6, IL-8, ICAM-1, CCl2, and OSM)." (PMID 31803630, 2019). "The role of ICAM-1 in carcinogenesis and drug resistance is often dependent on the cancer and cell type." (PMID 30791601, 2019). "ICAM-1 levels are elevated in the serum of patients with cardiovascular disease, autoimmune disorders, and cancer." (PMID 30868076, 2019). "In H59 Lewis lung carcinoma and A549 human lung carcinoma, MAC-1 on neutrophils acts as a bridge between ICAM-1-expressing cancer cells and endothelial cells in favor of liver metastasis." (PMID 31474975, 2019). "Its binding to cancer cells is mediated through intercellular adhesion molecule 1 (ICAM-1) and decay-accelerating factor (DAF)." (PMID 30426287, 2018). "OS-HMW antimetastatic effects have been related to heparanase inhibition and to the ability to lower cancer cell adhesion to endothelial cells, and to intercellular adhesion molecule 1 and P-selectin." (PMID 30413079, 2018). "The CD103-E-cadherin interaction is required for polarized exocytosis of lytic granules, in particular, when ICAM-1 expression on cancer cells is missing, leading to target cell death." (PMID 30180905, 2018). "ICAM1 can facilitate the spread of metastatic cancer cells to secondary sites by recruiting inflammatory cells that release angiogenic and growth factors stimulating angiogenesis, cell proliferation, and invasion." (PMID 30414611, 2018). "There remains confounding information on the relationship of ICAM-1 expression and prognosis in a range of cancers." (PMID 30116025, 2018). "Our finding that blockade of ICAM-1 increments lymphocyte migration to the lymph nodes opens important perspectives for the treatment of cancer." (PMID 30258446, 2018).
cancer (continued). "ICAM1 is an important molecule for lymphoid trafficking and has been shown to be upregulated in several types of cancers, including breast cancer." (PMID 30082828, 2018). "The cancer cells that survive in the bloodstream become attached to the secondary site and the adhesion molecules, such as ICAM-1 and integrin β1, affect the adhesion process." (PMID 29459827, 2018). "Among them, HLA class I antigens, the co-stimulatory molecule ICAM-1, and tumor-associated antigens (TAA), such as the cancer testis antigens (CTAs) NY-ESO-1 and MAGE-A3 that are considered suitable therapeutic targets due to their high immunogenic potential." (PMID 30581389, 2018). "Concurrently, protein expression levels of VCAM-1, ICAM-1, resistin, biomarkers in plasmas are clearly up regulated during initial stage of cancer, but significantly down regulated in later stages of cancer in patients." (PMID 29606130, 2018). "In this review, we have commented on studies that report a link between either the integrin LFA-1 or its ligand ICAM-1 and cancer." (PMID 29099772, 2017). "We elucidated two anti-tumorigenic mechanisms of E3 ligase FBXO4: reduction of ICAM-1 stability and suppression of cancer cell migration and invasion." (PMID 29137327, 2017). "Published literature has shown increased resistance to NK cell-mediated lysis due to MHC-class I upregulation in some cancers, but increased sensitivity to NK cell-mediated lysis due to ICAM-1 upregulation in others." (PMID 28428785, 2017). "A more recent study showed that ICAM-1 is a potential membrane stem cell marker in ERSCC cancer cell lines." (PMID 28930282, 2017). "KCa3.1 channels regulate ICAM-1 dependent cell-cell adhesion between endothelial and cancer cells that affects the transmigration step of the metastatic cascade." (PMID 29348824, 2017). "We demonstrate that the membrane-bound ICAM-1 isoform is necessary and sufficient to promote inflammation-dependent extracellular matrix contraction, which favors cancer cell invasion." (PMID 27901489, 2017). "This experimental evidence implies that inflammatory responses mediated via the cancer cell-derived TF-fVIIa complex and ICAM-1 play vital roles in EOC progression." (PMID 28417928, 2017). "ICAM-1 is thus identified as a crucial regulator of the inflammation-dependent ECM remodeling in cancer." (PMID 27901489, 2017). "Src activation and ICAM-1 phosphorylation in cancer cells can not only be induced by incubation with TNFα but also be blocked by clinically relevant concentrations of lidocaine and ropivacaine." (PMID 29326939, 2017). "Future studies should investigate the application of the adhesion molecule ICAM-1 to cancer therapy." (PMID 28903329, 2017). "According to these findings, it was proposed that an efficient targeting of ESCC cancer stem cells should involve dual targeting of both ICAM-1 and CD44." (PMID 28930282, 2017). "MMP-9 and ICAM-1 are critical to the invasion and metastasis of cancers, therefore serve as markers for assessing the invasiveness of our cellular model." (PMID 28903398, 2017). "That is, ICAM-1 stability and cancer progression appear to be modulated by the post-translational regulation of ICAM-1, and not transcriptional regulation." (PMID 29137327, 2017). "We also observed the increased expression of two alternative transcripts (TRIB3: uc002wdm/NM_021158 and ICAM1: uc010xle/AK301412) in all the cancers with one exception." (PMID 28105922, 2016). "ICAM1 is a cell surface molecule typically expressed on endothelial cells, cells of the immune system, cancer cells and mesothelial cells." (PMID 27074785, 2016). "The up-regulation of uc010xle/AK301412 (ICAM1) level was detected in breast (50%, 30 of 15, p < 0.05), prostate (50%, 30 of 15, p < 0.05), and kidney (70%, 21 of 30, p < 0.05) cancers." (PMID 28105922, 2016). "ICAM-1 is highly expressed in cancer and involved in PBL and PMN adhesion to endothelium, as shown by function blocking studies." (PMID 26943029, 2016).
cancer (continued). "Involvement of LFA-1/ICAM-1 in the immune response against cancer cells has been indicated both in vitro and, more recently, in vivo." (PMID 27447568, 2016). "Owing to the critical role of ICAM-1 expression in cancer pathogenesis, inhibition of ICAM-1 by HE treatment would be a valuable approach to inhibit cancer cell migration and the spread of cancer cells to distant organs, or both." (PMID 26823953, 2016). "More importantly, coculture of ICAM-1−/− macrophages with apoptotic cancer cells resulted in an increase of M2-like macrophages, which was blocked by an efferocytosis inhibitor." (PMID 26068788, 2015). "We also assessed the involvement of ICAM-1, the ligand for these integrins, on A549 cancer cells using a neutralizing antibody." (PMID 26231039, 2015). "Genetic silencing through transfection with siRNA of EGFR or ICAM-1 and pretreatment with inhibitors of EGFR, PI3K, Akt, NF-κB and IKK abrogated the AREG-enhanced ICAM-1 expression and cancer cell migration." (PMID 26503469, 2015). "ICAM1 promotes cancer cell migration, invasion as well as increasing mesenchymal marker expression and attenuating epithelial marker expression." (PMID 26571024, 2015). "Our findings on the role of macrophage ICAM-1 in efferocytosis will provide a new therapeutic strategy for cancer metastasis." (PMID 26068788, 2015). "In line with its antitumorigenic responses observed in vitro, ICAM-1 expression has been likewise reported to be negatively correlated with metastasis of several cancer types in clinical studies." (PMID 26513172, 2015). "The pharmaceutically-formulated HAMPT inhibited adhesion of cancer cells to either endothelial cells or extracellular matrix via down-regulating cell adhesion molecules ICAM-1 and α4-integrin." (PMID 26459390, 2015). "The breaching of LEC barriers by MCF-7 spheroids is stimulated by NF-κB-driven expression of ICAM-1 and by NF-κB-dependent repression of VE-cadherin in LECs supporting the fact that NF-κB stimulates cancer metastasis." (PMID 26513020, 2015). "We found that both inhibitors suppressed the AREG-induced cancer cell migration and ICAM-1 expression in mRNA and protein levels." (PMID 26503469, 2015). "ICAM-1 mRNA expression levels were markedly increased in the M2 macrophages isolated from the developing carcinoma and metastatic tissues of the AOM/DSS mice, as compared with the M1 macrophages." (PMID 25434400, 2015). "Using the 3D microfluidic assay, we showed that ICAM-1 was involved in carcinoma aggregate cell dissociation and migration." (PMID 26231039, 2015). "Because cell adhesion molecules have been shown to be critical in cancer cell metastasis, we examined the effect of resistin on the ICAM-1 and VCAM-1 mRNA and cell surface protein expressions in SK-Hep1 cells." (PMID 24555415, 2014). "We also observed cytotoxicity of NK cells to cancer cells was enhanced by increasing ICAM-1 mediated by E2F1 knockdown." (PMID 24742333, 2014). "We first investigated role of VAP-1 and ICAM-1 on the adhesion of cancer cells in the TMNK-1 containing cultures." (PMID 24900957, 2014). "ICAM-1 expression has been correlated with progression, prognosis and aggressive phenotype in cancer." (PMID 24344116, 2014). "Possible counter receptors for these interactions are CD43 and MUC1, two known ligands for ICAM-1 which are expressed by these cancer cells." (PMID 24857933, 2014). "Several cell adhesion molecules (CAMs), including intercellular adhesion molecule-1 (ICAM-1) and vascular cell adhesion molecule-1 (VCAM-1) have been implicated in cancer growth, and metastasis." (PMID 25156554, 2014). "ICAM-1 is constitutively expressed highly in hLSECs and plays an important role in the interactions with cancer cells." (PMID 24900957, 2014). "Several lines of evidence in this study showed that, in addition to its role in leukocyte adhesion and cancer cell invasion, ICAM-1 plays an important role in IL-6-mediated cancer metastasis." (PMID 24398980, 2014).
cancer (continued). "Then, we evaluated the role of VAP-1 and ICAM-1 on the adhesion of cancer cells in HUVECs containing cultures." (PMID 24900957, 2014). "Several adhesive molecules, such as intracellular adhesion molecule-1 (ICAM-1), have been identified as being responsible for the endothelial adhesion of cancer cells." (PMID 23874773, 2013). "ICAM-1 is an important adhesion molecule during the adhesion between endothelial cells and cancer cells which is an essential step in cancer invasion." (PMID 23803661, 2013). "Activation of endothelial cells by IL-1β induced the expression of ECAMs namely VCAM-1, ICAM-1 and E-selectin on endothelial cell surfaces, and these proteins facilitated the binding of cancer cells." (PMID 23460862, 2013). "Cancer cell-endothelial cell interaction is mediated by various adhesive molecules such as intracellular adhesion molecule-1 (ICAM-1), vascular cell adhesion molecule-1 (VCAM-1) and E-selectin." (PMID 23874773, 2013). "Several lines of evidence in this study show that, in addition to its role in leukocyte adhesion and cancer cell invasion, ICAM-1 plays an important role in WISP-1–mediated cancer metastasis." (PMID 24205072, 2013). "To determine the clinical significance of WISP-1 and ICAM-1 expression in patients with cancer, we analyzed samples from OSCC patients by immunohistochemical staining." (PMID 24205072, 2013). "Cell adhesion molecules (CAMs), such as vascular endothelial cell adhesion molecule-1 (VCAM-1), intercellular cell adhesion molecule-1 (ICAM-1), and E-selectin, have been shown to be essential for endothelial cells in interaction with the cancer cells." (PMID 23460862, 2013). "It is known that cancer cell-endothelial cell interactions are regulated in part by the expression of specific adhesion molecules on the cell surface, such as ICAM-1." (PMID 22028734, 2012). "As a member of the immunoglobulin superfamily, it has been reported that sICAM-1 is immunosuppressive and local release of ICAM-1 appears to promote local immune tolerance and cancer cell immune escape." (PMID 22641338, 2012). "Since aberrant regulation of the transcription factor NF-κB and its signaling pathways are involved in cancer development and progression, and the induction of ICAM-1 involves activation of NF-κB, the effects of GJH on NF-κB were examined." (PMID 22028734, 2012). "It has been reported that the serum level of soluble (s)ICAM-1 is elevated in patients with cancers." (PMID 23098564, 2012). "In the present study, we therefore determined whether ICAM-1 was a critical mediator of cancer-derived TSP4." (PMID 41399375, 2026). "LKB1 mutant cancer cells lead to significant inhibition of ICAM1." (PMID 40568576, 2025). "In addition, adhesion molecules, such as ICAM-1, play a role in metastasis in various types of cancer." (PMID 41302385, 2025). "In addition to its role in cancer dissemination, evidence suggest that ICAM-1 also plays a role in cancer angiogenesis." (PMID 40071851, 2025). "Furthermore, the downregulation of integrins such as ICAM1, which has been shown to be important in anti-cancer immunity, was also observed." (PMID 39860532, 2025). "miRNAs such as hsa-mir-196a-5p and hsa-mir-29a-5p regulate the expression of cell adhesion molecules, including CD44, ICAM1, and ITGA3, and may therefore be associated with cell migration and cancer metastasis." (PMID 41226241, 2025). "Additionally, bilateral cancer‐endothelial interactions are revealed, aggressive cancer cells induce significant intercellular adhesion molecule‐1 (ICAM‐1) upregulation in endothelium." (PMID 40223399, 2025). "CD9 is also shown to associate directly with ADAM17 on the surface of different cell types (cis interactions), including leukocytes and cancer cells, and through this association exerts an inhibitory effect on ADAM17 sheddase activity against its substrates, including TNFα, ICAM-1 or ALCAM." (PMID 38542421, 2024). "ICAM-1 plays an essential role in inflammation and cancer metastasis." (PMID 38892215, 2024).